IL37 (interleukin 37)
Diseases named in the same sentence as IL37 in open-access papers (continued):
Sharing a sentence is not in itself a finding about the gene and the disease.
Stroke (7 papers, 2017 to 2025). Sudden impairment of blood flow to a part of the brain due to occlusion or rupture of an artery to the brain. "In a logistic model adjusted for other factors, IL-37 in the highest quartile (>405.3 pg/ml) was still associated with recurrent stroke (OR = 3.32; 95%CI = 2.03-6.13; P < 0.001)." (PMID 33953828, 2021). "Second, this was associated with augmented abundance of IL-37 in the ischemic brain tissue of one stroke patient and in mice." (PMID 31061403, 2019). "There was one patient with dissection as the cause of a small stroke where the IL-37 level was negligible." (PMID 29234571, 2017). "For instance, the presence of IL-37 in the brain after stroke, observed in both human post-mortem tissues and mouse models, is associated with reduced microglial activation, suggesting that IL-37 modulates post-stroke inflammation in the brain." (PMID 40332510, 2025). "In addition, other biomarkers such as serum fatty acid binding protein 4 (FABP4), serum CXCL12 levels, interleukin-37, and cystatin C have been reported to be associated with stroke recurrence." (PMID 37051146, 2023). "Whether this surge in IL-37 is a factor limiting further stroke-related inflammation or something that causes tissue damage is difficult to infer from this small pilot project." (PMID 29234571, 2017). "Increased serum IL-37 in ischemic stroke patients is correlated with stroke recurrence and 3-month functional prognosis." (PMID 35173738, 2022). "This was associated with 2.7-fold greater lung expression of Il-10 mRNA (P = 0.006), whereas in contrast to brain, IL-37 mRNA in the lungs tended to be reduced by stroke (P = 0.075)." (PMID 31061403, 2019). "Expression of this splice variant is therefore ubiquitous in these mice, including in the brain cells or in immune cells infiltrating the brain, thus allowing us to investigate the effects of IL-37 in various disease settings including stroke." (PMID 31061403, 2019). "Post-stroke plasma IL-37 abundance on day 3 was similar to that recorded within 2 days of stroke onset (170 ± 245 pg/ml)." (PMID 31061403, 2019). "Secondly, here we investigated the effect of IL-37 on post-stroke outcome at 24 h only, and it will be important to clarify if the IL-37-dependent protective effects are sustained over a longer period." (PMID 31061403, 2019). "To investigate the regulation of IL-37 in the setting of stroke, we explored IL-37 protein and mRNA in humans after stroke and in mice in a model of this disease." (PMID 31061403, 2019). "Our findings reveal that IL-37 is augmented in the brain and plasma following ischemic stroke, and exerts protection by modulating post-stroke inflammation in the brain and periphery." (PMID 31061403, 2019). "In summary, this study has provided the first data assessing the effect of ischemic stroke on the regulation of IL-37 in humans and IL-37tg mice, and of the impact of IL-37 on stroke outcome measures." (PMID 31061403, 2019). "The other cases with lab collection from stroke onset between 3 - 24 hours had IL-37 levels in the range of 500 - 1,900 pg/ml." (PMID 29234571, 2017). "Three of them presented acutely within three hours of stroke onset with IL-37 serum levels being 2,655 pg/ml, 3,517 pg/ml, and 5,235 pg/ml." (PMID 29234571, 2017). "A prospective "CRISP" trial is registered with the ClinicalTrials.gov (Identifier: NCT03297827) to determine the role of IL-37 in modulating post-stroke inflammation." (PMID 29234571, 2017). "Three patients who presented within three hours of stroke onset had IL-37 serum levels of 2,655 pg/ml, 3,517 pg/ml, and 5,235 pg/ml, respectively." (PMID 29234571, 2017). "IL-37 plays a certain role in mediating post-stroke inflammation with a significant increase in serum levels of this novel cytokine observed in ischemic stroke patients." (PMID 29234571, 2017). "The serum levels of IL-37 in six stroke patients and urine levels in eight stroke patients were available, measured by RT-PCR and ELISA." (PMID 29234571, 2017).
Stroke (continued). "However, another study has illustrated that IL-37 exert protective effects by modulating post-stroke inflammation in the brain and periphery." (PMID 35173738, 2022). "Large randomized controlled trials should be carried out to confirm whether IL-37 lowering treatment improves stroke prognosis." (PMID 33953828, 2021). "Furthermore, we utilised transgenic mice for human IL-37 to similarly assess the effect of stroke on IL-37 regulation in that species, and to investigate the effect of IL-37 on brain injury, motor impairment and bacterial infection following stroke." (PMID 31061403, 2019). "However, brain expression of IL-37 mRNA was profoundly increased in IL-37tg mice specifically in the ischemic hemisphere after stroke (~7,000-fold; P = 0.005)." (PMID 31061403, 2019). "Our data show that IL-37 expression is increased following ischemic stroke in humans and IL-37tg mice, and may exert protective effects by modulating post-stroke inflammation in the brain and periphery." (PMID 31061403, 2019). "IL-37 may therefore have potential as a novel therapeutic approach in stroke, and future work to explore the therapeutic potential of post-stroke administration of recombinant IL-37 is therefore warranted." (PMID 31061403, 2019). "The multi-fold increase in the level of serum and urine IL-37, as is evident from our initial results, indicates a possible key role of this novel cytokine in post-stroke pathology as a modulator of brain inflammation and warrants further investigation in human populations." (PMID 29234571, 2017). "Based on these findings, our group has recently started a prospective clinical trial with the ClinicalTrials.gov (Identifier: NCT03297827) and acronym "CRISP" trial, which we hope will shed some light on the role of IL-37 in modulating post-stroke inflammation." (PMID 29234571, 2017). "Our pilot study showed IL-37 levels in urine in stroke patients ranging between 210 and 4,534." (PMID 29234571, 2017). "Our pilot project confirms the rise of IL-37 levels post-stroke in humans." (PMID 29234571, 2017). "Prior studies with healthy volunteers as a control group have consistently shown IL-37 plasma levels around or less than 65 pg/ml with maximum normal levels on ELISA approximated at 130 pg/ml.The role of IL-37 in stroke has remained elusive so far and lacks human studies." (PMID 29234571, 2017). "As seen for IL-37, several other anti-inflammatory markers, namely Foxp3 (P = 0.012), Ym1 (P = 0.006), Il-10 (P = 0.018), Il-13 (P = 0.002) and Tgfb (P = 0.008) were up to 3-fold increased in the ischemic hemisphere following stroke in IL-37tg compared to WT mice." (PMID 31061403, 2019). "IL-37 serum levels in those patients were higher than in those patients without stroke recurrence (417.0 pg/ml (IQR, 359.3-436.1) vs. 333.3 pg/ml (279.0-391.0))." (PMID 33953828, 2021). "As in human patients after stroke, plasma IL-37 was not correlated with post-stroke clinical scores in mice (ρ = 0.07, P = 0.733)." (PMID 31061403, 2019). "Our data show that plasma IL-37 was increased following stroke in both humans and IL-37tg mice, and that brain (but not lung) abundance of IL-37 was also augmented, consistent with its production being driven by pro-inflammatory signalling." (PMID 31061403, 2019). "Furthermore, there was a strong trend towards a negative correlation between brain expression of IL-37 mRNA and clinical score in mice after stroke (ρ = −0.50, P = 0.085), whereas this was not the case for plasma IL-37 protein (ρ = −0.07, P = 0.833)." (PMID 31061403, 2019). "Interleukin(IL)-37 is an immunosuppressive cytokine belonging to the IL-1 superfamily with no mouse homologue yet identified, the effects of which have not been studied in stroke." (PMID 31061403, 2019).
adult-onset Still disease (6 papers, 2015 to 2024). A rare inflammatory multisystem disorder characterized clinically by fever of unknown origin, arthralgia or arthritis, hyperleucocytosis, and typical skin rash. "The aim of this study was to evaluate the usefulness of serum interleukin (IL)-37 and IL-18 as disease activity markers of adult-onset Still’s disease (AOSD) and to compare their related clinical features." (PMID 33652679, 2021). "Adult-onset Still's disease (AOSD) is a systemic inflammatory disease characterized by a surge of cytokines such as interleukin (IL)-1, IL-6, IL-18, and IL-37." (PMID 38910713, 2024). "Interleukin (IL)-37 has been known to play an immunosuppressive role in various inflammatory disorders, but whether it participates in the regulation of pathogenesis of adult-onset Still’s disease (AOSD) has not been investigated." (PMID 29566725, 2018).
Chronic colitis (6 papers, 2015 to 2023). A chronic inflammatory disease of the large intestine (colon, cecum and rectum). "Here, we tested whether transgenic expression of human IL-37 protects IL-10 deficient (IL-10KO) mice from chronic colitis." (PMID 31781119, 2019). "The colon of WT mice (7.5 ± 0.3 cm) was significantly shorter than the colon of IL37+/+ mice (8.6 ± 0.3 cm) after the induction of chronic colitis (p < 0.01)." (PMID 30563054, 2018). "We determined the IL-37 expression in gut mucosal sites, and the effect of IL-37 on the development of chronic colitis." (PMID 30563054, 2018). "The histological scores significantly decreased after the induction of chronic colitis in IL37+/+ mice compared with WT mice." (PMID 30563054, 2018). "Most strikingly was the reduction of Tnfα, Cxcl10, and other proinflammatory and profibrogenic genes in livers of IL-37tg mice during chronic colitis suggesting that IL-37 modulates fibrosis both by inhibiting inflammation and downregulating fibrosis-inducing pathways." (PMID 33746950, 2021). "We recently reported that transgene IL-37 suppresses colon carcinogenesis in chronic colitis." (PMID 33746950, 2021). "We therefore hypothesized that IL-37 plays a protective role in the IL-10KO chronic colitis model and subsequent colon carcinogenesis." (PMID 31781119, 2019). "In the present study, we tested whether transgene IL-37 expression not only protects IL-10KO mice against chronic colitis but also against colon carcinogenesis." (PMID 31781119, 2019). "We examined here whether the expression of IL-37, an inhibitor of inflammatory and immune responses, could be detected on T-cells after the induction of chronic colitis." (PMID 30563054, 2018). "The effect of rhIL-37 protein could not be tested in CCl4-induced liver fibrosis or during chronic colitis due to the long-term nature of both models during which subcutaneous or i.p. injections would have induced an antibody response against human IL-37 protein." (PMID 33746950, 2021).
Graves disease (6 papers, 2014 to 2023). Graves' disease is an autoimmune disorder that leads to overactivity of the thyroid gland (hyperthyroidism).It is caused by an abnormal immune system response that causes the thyroid gland to produce too much thyroid hormones. "This study aims to measure the levels of serum and peripheral blood mononuclear cells (PBMCs) IL-37 in patients with Graves' disease and to examine its association with disease activity." (PMID 25226272, 2014). "The correlation of serum IL-37 levels with cytokines and disease activity in Graves' disease patients were investigated." (PMID 25226272, 2014). "However, the expression and role of IL-37 in Graves' disease (GD) remains unknown." (PMID 25226272, 2014).
idiopathic pulmonary fibrosis (6 papers, 2021 to 2025). Idiopathic pulmonary fibrosis (IPF) is a nonneoplastic pulmonary disease that is characterized by the formation of scar tissue within the lungs in the absence of any known cause. "IL-37-transgenic (-tg) mice were protected against a number of animal model diseases, including colitis, acute myocardial infarction, idiopathic pulmonary fibrosis (IPF), obesity-induced inflammation, allergic airway inflammation, and surgical operation-induced spinal cord injury, among others." (PMID 38067193, 2023).
lymph node metastasis (6 papers, 2016 to 2025). "Of note, this change of IL-37 concentrations was negatively correlated with histological grade, tumor size, lymph node metastasis and vessel invasion." (PMID 37928545, 2023). "In addition, the authors showed that IL-37 correlates with tumor size, lymph node metastasis, positive recurrence and residual tumor size." (PMID 41561739, 2025). "However, IL-37 expression was negatively correlated with histologic grade (χ2 = 26.972, P < 0.01, r = -0.563), tumor size (χ2 = 18.378, P < 0.01, r = -0.465), lymph node metastasis (χ2 = 39.178, P < 0.01, r = -0.679), and vessel invasion (χ2 = 19.552, P < 0.01, r = -0.480)." (PMID 32226541, 2020). "The high levels of IL-18 and low levels of IL-37 in the serum and PBMC of OSCC facilitate the development of advanced tumor stage and lymph node metastasis (the odd ratios of IL-18/IL-37 is 4.903 and 12.613, respectively)." (PMID 34248996, 2021). "Compared with OSCC patients with lymph node metastases, patients without lymph node metastases expressed higher levels of IL-37 protein." (PMID 37928545, 2023). "The group without lymph node metastasis displayed strong IL-37 staining, mainly at the cytoplasmic region, and the group with metastasis displayed moderate IL-37 expression at the canter of carcinoma nest." (PMID 27225603, 2016). "In addition, IL-37 expression was lower in OSCC with lymph node metastasis than those without metastasis (P < 0.01)." (PMID 27225603, 2016). "However, IL-37 expression was lower in OSCC cells with lymph node metastasis than in those without metastasis, suggesting that IL-37 may play a role in cellular transformation, but once cells become malignant, IL-37 functions to inhibit the tumorigenic process." (PMID 31231372, 2019).
pancreatic cancer (6 papers, 2020 to 2025). "In order to test the function of IL-37 in Gem treatment in vivo, we developed a subcutaneous pancreatic cancer mouse model using SW1990/pLV-Vector and SW1990/pLV-IL37 cells." (PMID 32226541, 2020). "IL-37 expression was decreased in pancreatic cancer, down-regulated IL-37-mediated gemcitabine resistance via interacting with HIF-1α and signal transducer and activator of transcription 3 (STAT3) and forming the HIF-1α/IL-37/STAT3 negative feedback." (PMID 32587480, 2020). "However, the roles of IL-37 in pancreatic cancer development and chemo-resistance remain unknown." (PMID 32226541, 2020). "Furthermore, it has been reported that interleukin-37 (IL-37) suppressed hypoxia-inducible factor-1α (HIF-1α) expression through STAT3 inhibition during the progression and chemoresistance of pancreatic cancer." (PMID 34193173, 2021).
periodontal disease (6 papers, 2018 to 2025). "Overall, we demonstrate that IL37 variants modulate the inflammatory cascade in periodontal disease." (PMID 30206230, 2018). "In RAW macrophages, PBMCs and transgenic mice, the IL37 variant increases expression of IL-1β and IL-6, inducing more severe periodontal disease, while IL-37 protein production is impaired and shows reduced cleavage by caspase-1." (PMID 30206230, 2018). "The IL-37 variants are found to not only be associated with a high inflammatory response, but also associated with more severe clinical manifestations of periodontal diseases." (PMID 30206230, 2018). "Another study, also using a set of databases, found 104 m6A-associated single-nucleotide polymorphisms (m6A-SNPs) to be associated with periodontal disease, and the rs2723186 m6A-SNP was identified as potentially regulating IL-37 gene expression in periodontal disease." (PMID 39629934, 2025). "Binding of IL-37 to the IL-18 receptor and to the decoy receptor 8 (IL-R8) causes a strong inhibition of innate immunity, which mediates acute inflammation and autoimmunity, including the pathogenesis of periodontal disease." (PMID 36362030, 2022). "This blockage of bone loss represents this biological function for IL-37 and suggests that IL-37 agonists might be a therapeutic target for preventing bone loss in inflammatory conditions, including periodontal disease." (PMID 30206230, 2018). "For example, subjects identified early in life to be at risk with one or more copies of the IL37 risk allele could receive more frequent preventive maintenance treatments in order to prevent the onset of periodontal disease." (PMID 30206230, 2018). "The study aimed to analyze how IL-37 responds in periodontal disease and its biological significance in gingival epithelial cells during inflammation." (PMID 40281482, 2025). "In periodontal disease, IL-37 expression was significantly higher in connective tissue compared to epithelial cells." (PMID 40281482, 2025). "This interplay highlights the potential of targeting NLRP3 and enhancing IL-37 as a therapeutic approach for the treatment of periodontal disease." (PMID 40267956, 2025). "Since IL-1 induces IL-33, it is pertinent to think that, by blocking IL-1 with IL-37, there would be an inhibition of inflammation in periodontal diseases; however, these data will need to be confirmed in the future." (PMID 36362030, 2022). "Due to the complexity of the periodontal microbiota and the diversity of the host response, it remains unknown whether IL-37 displays an immunoregulatory role in periodontal disease and how it reacts to infiltrating microorganisms." (PMID 40281482, 2025). "In fact, the suppression of excessive MMP-9 via elevated IL-37 levels might be an interesting new therapeutic approach in periodontal diseases." (PMID 40281482, 2025). "Since IL-37 is a strong blocker of IL-1 and a pro-inflammatory cytokine in periodontal disease, in this review, we speculate that IL-37 treatment of the disease could be a further therapeutic adjunct to traditional medications." (PMID 36362030, 2022). "Cytokines that are known as innate immunity cytokines such as IL-1, IL-6, and TNF-α and IFN-γ, IL-4, IL-10, IL-12, IL-17, IL-18, and IL-37 are some of the known proinflammatory and anti-inflammatory cytokines that have been studied in relation to periodontal diseases." (PMID 31308830, 2019). "We propose that there is a correlation between IL-37 and IL-1β levels and periodontal disease, and levels of IL-37 and IL-1β correlation may be an important parameter to evaluate the efficiency of the treatment of aggressive periodontal disease." (PMID 31308830, 2019). "Today, it is known that IL-37 inhibits innate and acquired immunity and, consequently, inflammation, an effect that could complement the treatment of acute and chronic gingival inflammation, including periodontal disease." (PMID 36362030, 2022).
periodontal disease (continued). "IL-37 production has not been previously reported in plasma cells and due to the dominance of plasma cells in the periodontal lesion, these cells may play an important role in periodontal disease pathogenesis and merit further investigation." (PMID 30206230, 2018).
renal cell carcinoma (6 papers, 2016 to 2024). "The level of IL-37 in the serum of renal cell carcinoma patients was significantly lower than that in a healthy control group and was negatively correlated with the TNM Classification of Malignant Tumors (TNM) stage of the tumor." (PMID 33489865, 2020).